PLEKHH1 (pleckstrin homology, MyTH4 and FERM domain containing H1)
Synonyms: KIAA1200
Tractability: PROTAC: ubiquitination databases record sites on it.
Gene: Protein-coding gene on chromosome 14 (67,533,290 to 67,589,612, forward strand). Ensembl gene ENSG00000054690.
Subcellular location (Human Protein Atlas): Centrosome
Gene Ontology:
Cellular component: cytoskeleton
Genetic constraint (gnomAD): Loss-of-function variants: 82 observed, 115.44 expected, observed/expected ratio (o/e) 0.71, 90% interval 0.59 to 0.85. The upper end of that interval is the gene's LOEUF score, 0.85, which puts it in group 3 of 6, group 1 being the genes least tolerant of losing a copy. Missense variants: 1,203 observed, 1,465.6 expected, observed/expected ratio (o/e) 0.82, 90% interval 0.78 to 0.86. Synonymous variants: 539 observed, 588.26 expected, observed/expected ratio (o/e) 0.92, 90% interval 0.85 to 0.98.
Homologues: Orthologues: chimpanzee PLEKHH1 (99% identical), macaque PLEKHH1 (97% identical), dog PLEKHH1 (87% identical), pig PLEKHH1 (87% identical), rabbit PLEKHH1 (86% identical), mouse Plekhh1 (83% identical), guinea pig PLEKHH1 (83% identical), rat Plekhh1 (83% identical), zebrafish plekhh1 (59% identical), Drosophila melanogaster CG43867 (39% identical), Caenorhabditis elegans max-1 (23% identical). Paralogues in human: PLEKHH2 (52% identical).
Diseases named in the same sentence as PLEKHH1 in open-access papers:
PLEKHH1 is named in the same sentence as 2 diseases in open-access papers, as found by Europe PMC text mining. Sharing a sentence is not in itself a finding about the gene and the disease.
PLEKHH1 shares sentences with these, for which no sentence is quoted: diabetes (1 paper); tumor (1).